MMP9 (matrix metallopeptidase 9)
Diseases named in the same sentence as MMP9 in open-access papers (continued):
Sharing a sentence is not in itself a finding about the gene and the disease.
tumor (continued). "MMP-9 is involved in tumor growth initiation and invasion in basal and squamous cell carcinomas and is associated with the radial growth phase of melanoma and tumor angiogenesis." (PMID 35457257, 2022). "Finally, the secretion of IL-6 by endothelial cells in the tumor microenvironment is also capable of activating MMP9 and causing tumor remodeling." (PMID 36497411, 2022). "Remodeling the immunogenicity of tumor cells may be one of the reasons underlying the improved prognosis of patients with MMP9-High SCLC after cisplatin treatment." (PMID 35431936, 2022). "Interestingly, α3β1 has been associated with tumor-cell invasion and has been shown to regulate MMP-9 RNA stability in keratinocytes." (PMID 35269439, 2022). "The -1562 C/T transition, MMP-9, and acetylated c-Jun were associated with the presence of extra-thyroid invasion and degree of tumor infiltration, while the T allele and acetylated c-Jun also correlated with tumor stage." (PMID 36010303, 2022). "Both MMP-2 and MMP-9 are associated with tumor invasion, metastasis and angiogenesis." (PMID 36016565, 2022). "Additionally, MMP9 was reported to have a tumor suppressor role in colitis-associated cancers (CACs) by the activation of Notch1-dependent intracellular signal transmitters that triggered cell apoptosis, cell-cycle arrest, and DNA damage." (PMID 35406619, 2022). "MMP-2 and MMP-9 have been strongly linked to angiogenesis, invasion, and metastasis in tumor cells." (PMID 33994999, 2021). "MMP9 is not only known to be associated with EMT but also with tumor cell migration and invasion." (PMID 35096817, 2021). "Additionally, elevating the expression of MMP2 and MMP9 in ovarian cancer cells causes increased tumor growth and metastasis in both direct and indirect co-cultures with hADMSCs." (PMID 33849537, 2021). "Additionally, transcription factors, including NF-κB, AP-1, and Sp-1, have been closely linked with MMP-9 expression in tumor cells." (PMID 33430488, 2021). "Matrix metalloproteinase-9 (MMP-9) has functional roles in tumor angiogenesis, invasion, and metastasis, and is associated with cancer progression and poor prognosis, suggesting that inhibitors of MMP-9 activity and transcription are prime candidates for cancer therapy." (PMID 34769032, 2021). "The expression of MMP9 was positively associated with the abundance of six immune in tumor tissues." (PMID 33643387, 2021). "Increased expression of MMP-9 in vitro and in vivo has been linked to tumor progression." (PMID 34976811, 2021). "Moreover, the expression of MMP2 and MMP9, tumor metastasis-associated molecules, were reduced after silencing CD151 expression." (PMID 34108040, 2021). "MMP9 is profoundly implicated in the invasion, metastasis, and angiogenesis of various tumors including non-small cell lung cancer, cervical cancer, ovarian cancer, and pancreatic cancer and can mediate the tumor microenvironment." (PMID 33809973, 2021). "Matrix metalloproteinase 9 (MMP-9) is a zinc-containing endopeptidase that participates in the degradation of the extracellular matrix and vascular reconstruction and is associated with tumor invasiveness and progression." (PMID 34778039, 2021). "In murine, MMP-9 has been shown to play a role in tumor-associated tissue remodeling." (PMID 33091333, 2021). "MMP2 and MMP9 were markers closely associated with tumor invasion and metastases." (PMID 34479497, 2021). "Clinically, MMP-9 secreted by tumor-associated macrophages (TAMs) has been linked to stress." (PMID 33810259, 2021). "Interestingly, both putative targets, Mmp9 and Bv8, were significantly upregulated upon stromal Junb loss both in the primary tumor and early metastatic lungs." (PMID 34282521, 2021). "The current sequencing experiment from different tumour sampling sites enabled the detection of tissue-specific cells, such as Langerhans-like dendritic cells (DC_CD207) and lipid-associated macrophages (M_MMP9) enriched in the omentum." (PMID 34238352, 2021).
tumor (continued). "linked the EGFR expression with MMP-9 upregulation in tumor cells in vitro in NSCLC patients." (PMID 34976811, 2021). "Furthermore, it was validated using mouse model experiment that circSETDB1 depletion repressed tumor growth and decreased the expression of metastasis-related MMP9 and MMP2 as well as proliferation-linked ki-67." (PMID 34789310, 2021). "However, for colitis-associated colon cancer, MMP9 has a protective role and acts as a tumor suppressor." (PMID 34804973, 2021). "Moreover, MMP-2 activity is required for the angiogenic switch during tumor development and has, together with MMP-9, been implicated in the regulation of expression and release of vascular endothelial growth factor (VEGF)." (PMID 34055644, 2021). "Even though MMP-2 and MMP-9 represent the most investigated MMPs in the context of radiotherapy, also other family members have been associated with the remodeling of the irradiated tumor microenvironment." (PMID 34055644, 2021). "In addition, we also found that enalapril and 5-FU together significantly inhibited the expression of MMP-2 and MMP-9 in vivo, which are also associated with tumor invasion and metastasis, and are regulated by NF-κB/STAT3 pathway." (PMID 32581212, 2020). "In addition, tumor-associated macrophages secrete an active form of MMP-9 that can stimulate tumor cell migration and invasion by the proteolytic cleavage of matrix constituents." (PMID 33086476, 2020). "MMP-9 is a pro-angiogenic factor and has been associated with tumor angiogenesis and progression." (PMID 31945777, 2020). "In tumor tissues, the control of MMP-9 production is altered or lost due to several causes." (PMID 32630531, 2020). "Accordingly, MMP-9-deficient MDSCs fail to induce tumor angiogenesis." (PMID 32913278, 2020). "Furthermore, the role of PRDX1 in promoting tumor metastasis was associated with increased expression of Snail and MMP-9 and decreased expression of E-cadherin." (PMID 31956363, 2020). "In vitro experiments showed that, inhibition of the CD44-MMP axis may provide therapeutic targets for reducing the tumour spread which further establishes a positive association between MMP9 and CD44 expression." (PMID 32445177, 2020). "Similarly, on the tumor cell membrane, MMP-9 proteolitically cleaves natural killer group 2 member D ligands, thereby lowering tumor cell susceptibility to natural killer cells." (PMID 32630531, 2020). "Once activated, MMP-9, secreted by tumor-associated neutrophils (TANs), cleaves various PGs in the extracellular space, destroying the existing tissue structure, releasing angiogenesis-related factors, and opening up space for expanded tumors to enhance angiogenesis." (PMID 32825245, 2020). "MMP-9 expression is also significantly associated with tumor grade." (PMID 32944046, 2020). "Using orthotopic and metastatic prostate cancer mouse models, inhibition of the VEGF/VEGFR axis by an antibody (DC101) against the VEGF receptor, flk-1, reduced tumor-induced angiogenesis and suppressed metastasis, and this was associated with diminished MMP9 production by endothelial cells." (PMID 32585812, 2020). "MMP2 and MMP9, as important members of the gelatinase family of MMPs which degraded type IV collagen, the principal component of the basement membrane, cause increased tumor metastasis." (PMID 33381605, 2020). "Experimental metastasis studies have also shown that the downregulation of MMP9 expression in cancer cells by ribozyme could reduce tumor foci in the lungs of mice, consistent with the results observed in Mmp2- or Mmp9-deficient mice." (PMID 32708426, 2020).
tumor (continued). "The potential clinical relevance is less pronounced, as just half of the studies reported associations between increased MMP2 or MMP9 levels with clinical characteristics such as survival, metastasis or tumor stage, whereas in the other half of the studies no such correlations were observed." (PMID 32325664, 2020). "Moreover, the upregulation of MMP-9 expression and activity is associated with tumor angiogenesis, invasion, and metastasis when IL-7 is overexpressed as well." (PMID 31185636, 2019). "Furthermore, high levels of tumor infiltrated macrophage-derived MMP-9 found in CRC specimens have been associated with high risk of metastasis and poor disease outcome, as MMP-9 promotes degradation of the type IV collagen of the basement membrane." (PMID 31614860, 2019). "MMP9 is a metalloproteinase from gelatinase class, which is classically involved with degradation of elements harbored within the basal membrane, such as collagens, a biological event highly associated with tumor invasion." (PMID 31096664, 2019). "Moreover, we studied the expression of MMP9 as its expression by MDSCs has been linked to their tumor-promoting potential." (PMID 31212684, 2019). "Moreover, cluster of differentiation 147 (CD147) and MMP-9, two strains of HO-l mediated protein associated with tumor cell invasion and metastasis, also showed increased expression that as a consequence enhanced tumor cell invasiveness." (PMID 31337431, 2019). "In addition, we also detected the expressions of E-cadherin, N-cadherin, Matrix metalloproteinase (MMP)-2 along with MMP-9, which are closely associated with tumor metastasis capacity by western-blot." (PMID 31164797, 2019). "Furthermore, MMP-9 from inflammatory cells, particularly neutrophils and tumor-associated macrophages (TAMs), codetermines prognosis and outcome." (PMID 30669448, 2019). "In particular, MMP9 promotes tumor growth, migration, as well as tumor-associated inflammation." (PMID 31533268, 2019). "The changes of tumor volume, body weight, NF‐κB activation, MAPK activation, and tumor progression‐associated proteins (MMP‐9, XIAP, VEGF, and Cyclin‐D1) after regorafenib treatment were evaluated with digital caliper, digital weight, and ex vivo Western blotting assay." (PMID 30801954, 2019). "In addition, MMP-2, known as another gelatinase of MMP family except for MMP-9, is also associated with tumor invasion in PAs." (PMID 32922863, 2018). "Additionally, matrix metalloproteinases (e.g., MMP-8 and MMP-9) derived from tumor associated neutrophils (TAN) further contribute to the immunosuppressive nature of the tumor microenvironment." (PMID 30400571, 2018). "However, high expression of MMP2 and MMP9, alone and in combination has been associated with tumour progression in HCC." (PMID 29346427, 2018). "In addition, expression of proteins associated with anti-tumor immunity (eg, IL-12 and IL-18) was increased upon anti–MMP-9 and anti-PDL1 antibody combination treatment." (PMID 30500835, 2018). "Matrix metallopeptidase 9 (MMP9) was found to be associated with tumor aggressiveness." (PMID 30013825, 2018). "Both MMP-2 and MMP-9 are markers associated with the tumor invasion and metastasis." (PMID 30960968, 2018). "In addition, several mouse models have revealed that MMP9 deficiency increases tumor progression and invasiveness." (PMID 30174795, 2018). "Importantly, TIPE1 dramatically restrained the expression and activities of MMP2 and MMP9 which are demonstrated to promote tumour progression and are implicated in EMT." (PMID 28994231, 2018). "Our clinico-pathological data showed that FoxM1 over-expression was significantly associated with VEGF and MMP-9 expression, proteins implicated in tumor angiogenesis and extracellular matrix degradation respectively, thereby allowing cancer cells to invade and migrate to surrounding tissue." (PMID 29707121, 2018).
tumor (continued). "NET components MMP9, cathepsin G and neutrophil elastase are all known to contribute to extracellular matrix remodeling as well as provide signals for tumor cell proliferation, migration and tumor-associated angiogenesis." (PMID 30356678, 2018). "These authors additionally identified an association between MMP-9 overexpression and tumor depth." (PMID 30271341, 2018). "In addition, studies have reported that cyclin D1, cyclin E, MMP-2 and MMP-9 are associated with tumor growth and metastasis inhibition in an A549 cell and its xenograft mouse tumor model." (PMID 29522490, 2018). "MMP-7 and MMP-9 are the main proteases of zinc-dependent endopeptidases and participate in extracellular matrix degradation, which is associated with the movement of tumour cells." (PMID 29466986, 2018). "MMP-9 overexpression is associated with enhanced tumor cell invasion and overall aggression." (PMID 28030810, 2017). "In addition, expression of MMP-9, which is associated with cell migration and extracellular matrix degradation, reflects the migration and invasion of tumor cells." (PMID 28422726, 2017). "Similarly, Sun and coworker showed that high expression of MMP-9 are strongly connected to the clinic-pathologic parameters including tumor size, capsule status, tumor stage and HCC recurrence risk." (PMID 28216578, 2017). "It recruits MMP9-positive tumor-associated macrophages and mediates cell migrations." (PMID 28841719, 2017). "In addition, Axl/14-3-3ζ signaling caused up-regulation of tumor-progressive TGF-β target genes including MMP9 and Snail34." (PMID 29259250, 2017). "The MMP2 and MMP9 promoter region contains cis-regulatory elements, including one NF-κB binding site, and NF-κB binding to this site is reportedly closely associated with tumor cell invasion." (PMID 27556184, 2016). "Reports also indicate the up-regulation of MMP2, MMP3, and/or MMP9 to be associated with tumor aggressiveness, suggesting that SIBLING-MMP complexes may facilitate tumor cell metastasis." (PMID 27331624, 2016). "The activation of MMP-9 in cancer has been associated with tumor growth and tumor spreading." (PMID 27115178, 2016). "Additionally, our results indicated that MMP9 played a major role in the THBS2-coexpressed gene network.MMP9 was reported to be involved in the progression of tumor metastasis and that it was associated with poor survival in NSCLC." (PMID 27513329, 2016). "Furthermore, FoxO3A activation has been also shown to cause tumor progression through induction of matrix metalloproteinase, such as MMP-9 and MMP-13." (PMID 25704884, 2015). "MDSCs also promote tumor-associated angiogenesis by secreting matrix metalloproteinase-9 (MMP-9)." (PMID 26078490, 2015). "The reduction in MMP2 and MMP9 levels was associated with retarded tumor cell migration." (PMID 26516076, 2015). "In the tumor microenvironment infiltrating cells, such as bone marrow cells, tumor associated macrophages and neutrophils have been shown to be a rich source of MMP-9 and tumor cells themselves express higher levels of MMP-9 compared to healthy tissue." (PMID 26219353, 2015). "MMP-9 and TN-C have been associated with tumor invasion and metastasis." (PMID 26652622, 2015). "TWEAK and its receptor, fibroblast growth factor-inducible protein 14 (Fn14), have recently been implicated in tumor cell pathogenesis and upregulation of MMP9, which is generally associated with poor disease prognosis due to its ability to promote tumor growth, migration, invasion, and metastasis." (PMID 25622756, 2015). "However, among patients with adenocarcinoma, tumor MMP-9 expression was associated with relapse (p = 0.003) and poor survival (p = 0.033)." (PMID 25888323, 2015).
tumor (continued). "MMP-2 and MMP-9 are enzymes that are implicated in the malignant progression of many tumor types." (PMID 26444270, 2015). "MMP-2 and MMP-9 are the important proteins associated with tumor cells invasion characteristic." (PMID 25298750, 2014). "MMP9 has been implicated previously as a critical mediator in the processes of tumor angiogenesis and vasculogenesis, and so we also assessed the extent of tumor vascularization by staining the tumors for endothelial cell marker CD31." (PMID 24811362, 2014). "Plasticity in tumour inflammatory infiltrates, therefore, can alter tumour-associated protease expression to compensate for gelatinase B/MMP-9 loss, helping to explain the MMP inhibitor-induced tumour progression described in human late stage tumor clinical trials." (PMID 24473089, 2014). "Moreover, the downregulation of certain MMPs, such as MMP-9, contributes to TN-mediated inhibition of tumor cell invasion during metastasis: such reduction of MMP-9 levels has been also linked to inhibition of TGF-β signaling." (PMID 25295247, 2014). "It has been shown that MMP-9-deficient mice exhibit impaired metastasis formation and tumor growth." (PMID 24778099, 2014). "Within the tumour context, gelatinase B/MMP-9 was originally identified as a novel type IV collagenolytic protease secreted by metastatic Ras transformed fibroblasts and implicated in basement membrane disruption required for tumour invasion and metastasis." (PMID 24473089, 2014). "In this model gelatinase B/MMP-9 is required for tumor-associated vasculogenesis." (PMID 24473089, 2014). "Among them, MMP-9 has been implicated in tumor angiogenesis." (PMID 24527080, 2014). "This might result from increased tumor invasiveness due to enhanced MMP9 expression causing increased extracellular matrix breakdown." (PMID 24236052, 2013). "In addition, it has been demonstrated that high MMP-9 expression in UM tumours is associated with poor prognosis." (PMID 23914254, 2013). "Of the three genes found with significantly augmented expression in cocultures, two were proteases (MMP1 and MMP9), whose elevated expressions in the tumor microenvironment are associated with tumor cell invasion through increased degradation of ECM components." (PMID 23762835, 2013). "Although tumor-associated macrophages (TAM's) constitute the principal source of MMP9 in the zone of neoplastic growth, it should be noted that this molecule may be also synthesized by neoplastic cells, stromal neutrophils, fibroblasts, and mastocytes." (PMID 23576856, 2013). "Our findings further suggest that MMP9 may be linked to the role of GMCSF in tumor-associated pain, since both inflammatory and neuropathic mechanisms contribute to cancer pain." (PMID 24067145, 2013). "Of the MMPs, MMP-9 was found to be most closely linked to tumor grade." (PMID 24325546, 2013). "Accordingly, the aim of this study was to determine, using a multivariable model, the independent prognostic value of several immunohistochemically detected tumour-associated molecules, such as MMP-9 and uPA in stromal cells and Ki-67, TIMP-2 and VEGF in cancer cells." (PMID 23289974, 2013). "MMP9 (gelatinase B, 92 kDa gelatinase, 92 kDa type IV collagenase) degrades collagen IV and V. Murine studies suggest that it has a role in tissue remodeling associated with tumor development." (PMID 22897899, 2012). "Moreover, inflammatory cell-derived MMP-9 can drive tumor-associated angiogenesis by releasing VEGF." (PMID 23272179, 2012). "Furthermore, both MMP-9 and tumor size (T) were significantly but negatively associated with recurrence-free survival after adjusting for the other factor in multivariate analysis (p-value: T=0.050)." (PMID 22410369, 2012).